TSPOAP1 (TSPO associated protein 1)
Description:
Required for synaptic transmission regulation. It probably controls the recruitment of voltage-gated calcium channels to the presynaptic membrane, and modulates neurotransmitter release.
Synonyms: PRAX-1; PBR-IP; RIM-BP1; BZRAP1; KIAA0612; RIMBP1; DYT22; PRAX1
Tractability: No criterion of Open Targets' tractability assessment is met for any kind of drug.
Gene: Protein-coding gene on chromosome 17 (58,301,228 to 58,328,795, reverse strand). Ensembl gene ENSG00000005379.
Subcellular location: Cytoplasm; Mitochondrion
Pathways (Reactome):
Neuronal System: Acetylcholine Neurotransmitter Release Cycle; Dopamine Neurotransmitter Release Cycle; Glutamate Neurotransmitter Release Cycle; Norepinephrine Neurotransmitter Release Cycle; Serotonin Neurotransmitter Release Cycle
Metabolism: Pregnenolone biosynthesis
Gene Ontology:
Molecular function: benzodiazepine receptor binding; protein binding; voltage-gated calcium channel activity involved in regulation of presynaptic cytosolic calcium levels
Biological process: regulation of neurotransmitter secretion; neuromuscular synaptic transmission; regulation of presynaptic cytosolic calcium ion concentration
Cellular component: cytoplasm; mitochondrion; cytosol; calyx of Held; glutamatergic synapse
Genetic constraint (gnomAD): Loss-of-function variants: 87 observed, 181.53 expected, observed/expected ratio (o/e) 0.48, 90% interval 0.4 to 0.57. The upper end of that interval is the gene's LOEUF score, 0.57, which puts it in group 2 of 6, group 1 being the genes least tolerant of losing a copy. Missense variants: 2,166 observed, 2,395.5 expected, observed/expected ratio (o/e) 0.9, 90% interval 0.87 to 0.94. Synonymous variants: 911 observed, 978.74 expected, observed/expected ratio (o/e) 0.93, 90% interval 0.88 to 0.98.
Homologues: Orthologues: chimpanzee TSPOAP1 (97% identical), macaque TSPOAP1 (96% identical), pig TSPOAP1 (85% identical), rabbit TSPOAP1 (84% identical), dog TSPOAP1 (84% identical), guinea pig TSPOAP1 (83% identical), mouse Tspoap1 (82% identical), rat Tspoap1 (81% identical), tropical clawed frog tspoap1 (42% identical), Drosophila melanogaster Rbp (19% identical), Caenorhabditis elegans rimb-1 (16% identical). Paralogues in human: RIMBP3 (26% identical), RIMBP3C (26% identical), RIMBP3B (26% identical), RIMBP2 (25% identical).
Diseases named in the same sentence as TSPOAP1 in open-access papers:
TSPOAP1 is named in the same sentence as 17 diseases in open-access papers, as found by Europe PMC text mining. Sharing a sentence is not in itself a finding about the gene and the disease. The quoted sentences say what the papers report.
Alzheimer disease (4 papers, 2018 to 2025). A progressive, neurodegenerative disease characterized by loss of function and death of nerve cells in several areas of the brain leading to loss of cognitive function such as memory and language. "In conclusion, we found that three genes (APOE, PICALM, and TSPOAP1) associated with Alzheimer’s disease in EA are also associated with measure of cognitive functions in South Asians living in India, with the association primarily driven by missense/LoF SNVs." (PMID 39149469, 2024). "In conclusion, we found that three genes (APOE, PICALM, and TSPOAP1) associated with Alzheimer’s disease in EA are also associated with the measure of cognitive functions in South Asians living in India, with the association primarily driven by missense/LoF SNVs." (PMID 40565532, 2025). "It predicted quantity of phosphatidylglycerol, Alzheimer’s disease, progressive neurological disorder, adhesion of acute myeloid leukemia blast cells, and adhesion of human coronary artery endothelial cells (HCAEC) as the major diseases and functions associated with TSPOAP1." (PMID 34212002, 2021).
Dystonia (3 papers, 2022 to 2024). An abnormally increased muscular tone that causes fixed abnormal postures. "Furthermore, a recent study has shown that homozygous loss of TSPOAP1 causes pediatric-onset dystonia through synaptic abnormalities in the cerebellum, underscoring that aberrant synaptic function in the cerebellum can also cause dystonia in humans." (PMID 36960404, 2022).
acute myeloid leukemia (1 paper, 2021). Acute myeloid leukemia (AML) is a group of neoplasms arising from precursor cells committed to the myeloid cell-line differentiation. "TSPOAP1 through adhesion of acute myeloid leukemia cells promotes resistance to chemotherapy, including cytarabine." (PMID 34212002, 2021). "Therefore, TSPOAP1 can be explored as a potential drug target for drug-resistant acute myeloid leukemia." (PMID 34212002, 2021).
coronary artery disease (1 paper, 2021). "Based on its role in the adhesion of human coronary artery endothelial cells, TSPOAP1 may be a critical factor in various diseases, like atherosclerosis, and the development of TSPOAP1 ligands is a potential strategy for the treatment of coronary artery disease." (PMID 34212002, 2021).
metabolic syndrome (1 paper, 2021). A cluster of metabolic risk factors for CARDIOVASCULAR DISEASES and TYPE 2 DIABETES MELLITUS. "Taken together, the interaction of both TSPOAP1 and TSPO with these proteins supports the overlapping functions of TSPOAP1 and TSPO, including shared roles in inflammation, oxidative stress, metabolic syndrome, and cancer." (PMID 34212002, 2021). "Combining these pieces of information from the major signalling pathways of TSPOAP1 and TSPO, we can state that both proteins seem majorly involved in inflammation cascades and orchestrate a pivotal role in inflammation, oxidative stress, aging, cancer, and metabolic syndrome." (PMID 34212002, 2021).
cancer (4 papers, 2010 to 2022). A tumor composed of atypical neoplastic, often pleomorphic cells that invade other tissues. "A heat map analysis indicated that TSPOAP1 has critical roles in inflammatory, neuroinflammatory, psychiatric, and metabolic diseases and disorders, and cancer." (PMID 34212002, 2021). "TSPOAP1 deregulates phosphatidylglycerol and thereby impairs the activity of cardiolipin in the brain, which leads to progressive neurological disorders and cancer." (PMID 34212002, 2021). "Further research on TSPOAP1 could pave a way for the design and development of ligands targeting TSPOAP1 for the treatment of inflammatory diseases and cancer." (PMID 34212002, 2021). "As regulatory targets of some ncRNAs, TSPOAP1, ADGRG6, MMP28 and other genes are particularly important in the initiation, progression of various cancers such as PC." (PMID 34809653, 2021). "Our analysis also predicted that TSPOAP1 and TSPO strongly regulate sirtuin signalling, which may contribute to sirtuins mediated control and regulation of metabolism, oxidative stress, and DNA damage in inflammation and cancer." (PMID 34212002, 2021).
tumor (2 papers, 2020 to 2021). "Consistent with the WGCNA results, in the GSE15471 dataset, the TSPOAP1 in the tumor group was significantly lower expressed, while the ADGRG6, GPR87, FAM111B and MMP28 were significantly higher expressed compared with the normal group." (PMID 34809653, 2021).
TSPOAP1 also shares sentences with these, for which no sentence is quoted: autism (2 papers); asthma (1); Autoimmunity (1); brain diseases (1); breast carcinoma (1); chronic bronchitis (1); gastric cancer (1); glioma (1); neurological disorders (1); Pediatric onset (1).